DMD (dystrophin)
Diseases named in the same sentence as DMD in open-access papers (continued):
Sharing a sentence is not in itself a finding about the gene and the disease.
dystrophinopathy (continued). "While several preclinical models of dystrophin deficiency mimic point mutations or exon deletions, no existing rat model accurately replicates DMD gene duplications, which account for approximately 10% of DMD cases." (PMID 40490752, 2025). "Therefore, although it can identify DMD carriers, CK screening has only modest predictive value for patients with dystrophinopathy." (PMID 39075955, 2024). "The majority of these women will be asymptomatic, that is, DMD carriers, but these carriers may develop muscular symptoms or cardiac involvement, becoming patients with dystrophinopathy." (PMID 39075955, 2024). "A latter aspect is supported by the findings of another study which demonstrated that the analysis of DMD mRNA expression from skeletal muscle but not from lymphocytes led to the identification of a novel nonsense mutation in a carrier of dystrophinopathy." (PMID 39767645, 2024). "This is especially relevant to DMD, as it is known that the DMD gene contains several promoters that produce eight different tissue-specific dystrophin isoforms, as outlined in the below section on the genetic basis of dystrophinopathy." (PMID 38250815, 2024). "In that study, six dystrophinopathy carriers were identified at a carrier rate of 1:4088, but the identified DMD variants did not include the exon 49–51 deletion." (PMID 36424846, 2023). "Dystrophinopathies are caused by mutations in the dystrophin gene (DMD) that leads to the absence of or heavy reduction of dystrophin protein (DYS)." (PMID 36982290, 2023). "While those authors suggested this to be a Becker-type dystrophy, the early onset, near complete lack of dystrophin staining and DMD insertion predicting a CRM- pathology makes this more likely a Duchenne-type dystrophin deficiency." (PMID 36834603, 2023). "Usually, out-of-frame mutations result in the total absence of the protein and lead to DMD, the most severe form of dystrophinopathy, while in frame mutations that can determine partial, reduced or localized absence of dystrophin lead to more benign forms." (PMID 36672955, 2023). "One patient in the MLPA-negative DMD group who had clinical findings and muscle histopathology consistent with dystrophinopathy but with no variant found was believed to have a regulatory/promoter or deep intronic alteration." (PMID 36697461, 2023). "However, immunoblot analysis is a rapid and cost-effective alternative for detecting dystrophin alterations in dystrophinopathies." (PMID 37759719, 2023). "We next evaluated whether the dystrophin mutant dog shared a remarkably similar clinical course to that of dystrophinopathy patients." (PMID 35270040, 2022). "Furthermore, both reduced expression of sarcoglycans and dystrophin are observed in sarcoglycanopathies and dystrophinopathies; this makes it difficult to accurately predict the primary genetic defect among them based on muscle immunoanalysis." (PMID 35813381, 2022). "The perplexing genetic spectrum of dystrophinopathies, as a result of the high genetic complexity of the DMD gene, includes both large-scale copy number variation or structural variants (SVs) and small pathogenic DMD variants, which can occur in coding and/or non-coding regions." (PMID 36092865, 2022). "Notably, recent work from our group, and others, has suggested that uniform dystrophin expression is an important factor in the success of dystrophin restoration therapies and the severity of dystrophinopathies, respectively." (PMID 36159597, 2022). "The precise genetic diagnosis of a sarcoglycanopathy or dystrophinopathy is sometimes extremely challenging, as pathogenic non-coding variants and/or complex structural variants do exist in DMD or sarcoglycan genes." (PMID 35813381, 2022).
dystrophinopathy (continued). "Subsequently, segregation analysis and long-read sequencing showed that the DMD duplications identified in this family were benign variants, suggesting that the aborted fetus was not likely to have suffered from dystrophinopathies." (PMID 36360209, 2022). "A particular subset of DCM is encountered in a group of muscular disorders encompassed by the term dystrophinopathies, which are caused by mutations in the DMD gene which lead to the lack of a functional form of the dystrophin protein." (PMID 34573439, 2021). "Even though, it is well known that humans and rodents with dystrophinopathies have abnormal hearts, in our genetically modified rats, dystrophin immunostaining in skeletal muscle is normal, no dystrophinopathies, and no dystrophin mutations." (PMID 34063460, 2021). "Dystrophinopathy, a common neuromuscular disorder caused by the absence of dystrophin, currently lacks effective treatments." (PMID 33413615, 2021). "For example, in dystrophinopathy patients, the mRNA trapping by Dystrophin exonic circular RNAs might enhance the disease phenotype leading to inactive DMD transcripts, further reducing the pool of translatable mRNAs." (PMID 32467674, 2020). "If this analysis does not identify a pathogenic deletion or duplication and if dystrophinopathy is strongly suspected, then sequencing of the entire coding region of the DMD gene is recommended." (PMID 32424326, 2020). "In known dystrophinopathy families, previous genetic testing at the DMD locus may date as far back as the mid-1980s." (PMID 32424326, 2020). "Hence, in analogy to progressive forms of human dystrophinopathy, this animal model almost completely lacks the full-length dystrophin isoform Dp427-M." (PMID 32916630, 2020). "Immunofluorescence microscopy clearly confirmed the drastic reduction of ApoE in the mdx-4cv spleen and indicated that the expression of the short spleen-associated isoform of dystrophin is not affected in dystrophinopathy." (PMID 32916630, 2020). "PE inclusion, one of the non-canonical splicing events identified in DMD, has been reported to be implicated in various dystrophinopathies; however, its splicing characteristics have not been fully investigated." (PMID 33050418, 2020). "In conclusion, we identified a novel intronic DNA variant (c.7310-19A>G in intron 50) that caused a non-canonical splicing event in DMD (partial intron inclusion), expanding the genetic spectrum of aberrant splicing in dystrophinopathies in general." (PMID 33050418, 2020). "Considerable caution should be exercised when reporting results of haplotype analysis; the report document should clearly state that the interpretation assumes the diagnosis of dystrophinopathy in the family is correct (i.e. that the disorder is due to a defect in the DMD gene)." (PMID 32424326, 2020). "It is difficult to explain this phenomenon, but it is possible that a supplementary mechanism is responsible for the dystrophin defect, which should be investigated further and may be a novel target for treating patients with dystrophinopathies." (PMID 30833962, 2019). "Similarly to dystrophin, overexpression of utrophin can improve the membrane stability of dystrophic myofibers and suppress the functional signs of dystrophinopathy." (PMID 30304405, 2019). "The prevalence of dystrophinopathies in our study is 0.94/100,000 for DMD and 0.78/100,000 for BMD." (PMID 31791368, 2019). "Patients with dystrophinopathies show low levels of neuronal nitric oxide synthase (nNOS), due to reduced or absent dystrophin expression, as nNOS is attached to the dystrophin‐associated protein complex." (PMID 30106246, 2018). "The diagnostic evaluation of dystrophinopathy is proposed as follows: if staining for both the rod domain and C-terminus of dystrophin are absent in FFPE muscle sections, a diagnosis of DMD can be made." (PMID 28219397, 2017).
dystrophinopathy (continued). "For the most part, dystrophinopathies in other canine breeds have not been defined beyond immunohistochemical and Western blot studies demonstrating the loss of dystrophin." (PMID 28526070, 2017). "In order to further evaluate a dystrophin isoform lacking the actin binding domain encoded by exon 5, we induced a transient dystrophinopathy model by skipping Dmd exon 5 in wild-type mice." (PMID 26745801, 2016). "In the past, comparative proteomic studies using total muscle tissue extracts have greatly helped to improve our general understanding of the molecular pathogenesis of dystrophinopathies, but have mostly focused on alterations downstream of the dystrophin-glycoprotein complex." (PMID 28248273, 2015). "The proteomic screening of the microsomal fraction from dystrophic hind limb muscle identified the full-length dystrophin isoform Dp427 as the most drastically reduced protein in dystrophinopathy, demonstrating the remarkable analytical power of comparative muscle proteomics." (PMID 26067837, 2015). "In addition protein analysis has important prognostic value, as seen for example in dystrophinopathies, where the residual amount of dystrophin correlates better with the phenotype than the genetic prediction." (PMID 21798100, 2011). "However, the microdystrophin product is less effective functionally at complementing dystrophin deficiency than is the full-length cDNA, which is also a shortcoming of AAV-vector-mediated gene delivery for DMD." (PMID 17617925, 2007). "We herein included eight patients with dystrophinopathy (six males and two females) in whom pathogenic variants of the DMD gene could not be accurately identified using MLPA and NGS." (PMID 39575648, 2025). "For Duchenne, deletions and duplications are mostly out of frame, leading to severely reduced or absent dystrophin production, while Becker dystrophinopathy is more likely associated with in-frame deletions and duplications, granting some residual dystrophin production." (PMID 37834164, 2023). "In addition, our data may stimulate new studies on the structure and function of dystrophin proteins, dystrophin isoforms, and other epigenetic factors involved in dystrophinopathies." (PMID 37882106, 2023). "Additionally, this variant is commonly identified by CMA rather than by DMD‐specific testing, suggesting a dystrophinopathy is not initially specifically suspected at the time of testing." (PMID 36424846, 2023). "Despite major progress in treating skeletal muscle disease associated with dystrophinopathies, cardiomyopathy is emerging as a major cause of death in people carrying dystrophin gene mutations that remain without a targeted cure even with new treatment directions and advances in modelling abilities." (PMID 34445659, 2021). "Among all 931 foetuses (twins in one pregnancy were counted twice), 20.73% (193/931) were males expected to develop dystrophinopathies, 16.33% (152/931) were female carriers, 37.59% (350/931) were males without DMD mutations and 25.35% (236/931) were females without DMD mutations." (PMID 34238289, 2021). "Increasingly, genome-wide testing is being undertaken for many different clinical indications, and this may identify variants in the DMD gene in patients where a clinical diagnosis of dystrophinopathy has not been considered or suspected." (PMID 32424326, 2020). "Moreover, under certain conditions, concomitant reduction of dystrophin and sarcoglycans are observed in dystrophinopathies and sarcoglycanopathies, and of dystrophin and glycosylated α-DG in dystroglycanopathies; this hampers prediction of the primary genetic defect based on muscle immunoanalysis." (PMID 31747956, 2019). "Given the shared pathological mechanism between the loss of dystrophin and its associated proteins, such as sarcoglycans, this variant represented an attractive candidate modifier of human DMD, which was tested in the UDP severe dystrophinopathy cohort (n = 254)." (PMID 31083420, 2019).
dystrophinopathy (continued). "In cases of dystrophinopathies, as in BMD, the altered dystrophin protein leads to the replacement of myocardium by connective tissue and fat, which is more prominent in the posterobasal and lateral walls of LV." (PMID 38022137, 2023). "Results: 43 studies were included, reporting data on 1472 males with dystrophinopathies; with FSIQ scores available for 1234 DMD (k = 32) and 101 BMD (k = 7)." (PMID 36421868, 2022). "The ongoing Brain Involvement iN Dystrophinopathies (BIND) project aims at addressing this crucial aspect and will elucidate the role of dystrophin in the brain." (PMID 33671409, 2021). "Perhaps the most extensive of these would be the TREAT-NMD DMD Global Registry and the Leiden Open Variation Database (LOVD), each having data from more than 7000 dystrophinopathy patients across the world." (PMID 33238405, 2020). "Thus, the evaluation of future pharmacological studies or experimental gene therapeutic approaches for the treatment of dystrophinopathy should take into account that the deficiency in dystrophin does not affect all skeletal muscle subtypes in a similar manner." (PMID 23828267, 2013). "Duchenne and Becker muscular dystrophies (DMD and BMD) are dystrophinopathies caused by variants in DMD gene, resulting in reduced or absent dystrophin." (PMID 38693632, 2024). "It has an early onset of clinical manifestation and has the most severe form of dystrophinopathy due to the complete absence of the dystrophin protein." (PMID 39777119, 2024). "Functional muscle ischemia due to dysregulated blood flow to the muscle is a prominent feature in dystrophinopathies due to the absence of dystrophin in DMD and variable reduction in BMD." (PMID 39250335, 2024). "The study of biomarkers in a muscle partially spared from the absence of dystrophin allows us to identify dystrophinopathy markers that change with age, regardless of muscle degeneration." (PMID 37705069, 2023). "The recommended testing strategy to confirm the diagnosis of a dystrophinopathy in a male patient typically begins with deletion/duplication analysis of the DMD gene, followed by DMD sequencing if negative." (PMID 36424846, 2023). "A genetic diagnosis was pursued but initial investigation revealed no aberrations in the dystrophin gene (DMD), although immunohistochemistry and Western blot analysis suggested the diagnosis of dystrophinopathy." (PMID 37795243, 2023). "However, the precise genetic diagnosis of a sarcoglycanopathy or dystrophinopathy is sometimes extremely challenging, as non-canonical splicing site variants, deep intronic splice-altering variants (DISVs), and/or complex structural variants do exist in DMD or sarcoglycan genes." (PMID 35813381, 2022). "As for the 12 individuals with clinical presumptive diagnosis of dystrophinopathy but without identified pathogenic mutation, we could determine that five of them had a biopsy with immunohistochemistry compatible with dystrophinopathy (dystrophin deficient or absent)." (PMID 34149409, 2021). "In order to investigate the genotype–phenotype correlation in patients affected by dystrophinopathies and ASD, we conducted a literature search using a combination of the free-text terms “dystrophin” and “autism” on the Pubmed, Scopus, and Web of Science databases." (PMID 34640386, 2021). "In this study, dystrophin in the MT fraction of HEK293 cells was analyzed by western blot assay and compared to other human cancer cell lines, as well as primary cultured myocytes from three dystrophinopathy patients." (PMID 34575126, 2021). "Based on the expression pattern of dystrophin by quantitative method, the patients were classified into two groups: group 1 - DMD patients with the absence of dystrophin (30 cases), group 2 - BMD patients with dystrophin deficiency (10 cases)." (PMID 34950096, 2021).
dystrophinopathy (continued). "In DMD+/− pigs, a wide variation in serum CK activities was observed, ranging from levels within the cluster of WT pigs to highly elevated levels as in DMDY/− pigs, similar to human dystrophinopathy carriers." (PMID 34796900, 2021). "DMD, characterised by absent or non-functional dystrophin, is the most severe form of dystrophinopathy, with diagnosis in early childhood, and a progressive decline in muscle function and mobility." (PMID 32469921, 2020). "Among the aberrant non-canonical splicing events reported in the DMD gene, PE inclusion has been frequently described to be involved in the pathogenesis of dystrophinopathies." (PMID 33050418, 2020). "The pathogenesis of dystrophinopathy was previously linked to increased DNA damage and to increased mutagenesis in pluripotent stem cells reprogrammed from DMD patients and lacking dystrophin, as we showed previously." (PMID 32138751, 2020). "Although muscle biopsies for detecting dystrophin expression are not critical for the diagnosis of dystrophinopathies nowadays, quantification of dystrophin expression levels is helpful in classifying phenotypes." (PMID 30833962, 2019). "DMD, characterised by non-functioning dystrophin, is the most severe dystrophinopathy, with an estimated incidence of 3 in 100,000 boys." (PMID 30544630, 2018). "Each of these dystrophinopathies are characterised by either absent or reduced expression of the cytoskeletal protein dystrophin, resulting in progressive muscle degeneration with similar anatomical distribution but varied severity." (PMID 30544630, 2018). "For a full comprehension of the molecular and cellular complexity of dystrophinopathy, it is important to point out that dystrophin does not exist in isolation within the subsarcolemmal membrane cytoskeleton." (PMID 24772416, 2014). "This dystrophinopathy is generally characterized by large deletions of the dystrophin gene that do not alter the coding reading frame of the mRNA and that therefore, results in the expression of a shorter although partially functional dystrophin protein." (PMID 25405319, 2014). "Unlike previous studies conducted on the whole spectrum of dystrophinopathies, we stringently included patients without any residual dystrophin at Western blot." (PMID 19194511, 2009). "When anti-dystrophin is positive, dystrophinopathy is ruled out and LGMD is suspected, although LGMD may include a secondary decrease in dystrophin." (PMID 40757565, 2023). "In the case of dystrophinopathies, Pax7 cannot address the lack or complete absence of dystrophin." (PMID 37685856, 2023). "In dystrophinopathies the lack of different dystrophin isoforms also impairs CNS function." (PMID 34573206, 2021). "Our results suggest that altered WM connectivity and reduced fibre organization in cerebellar tracts, probably due to the lack of dystrophin in the brain, may render less efficient some neuropsychological functions in children affected by dystrophinopathies." (PMID 33939732, 2021). "Several authors reported frequent comorbidity between epilepsy and dystrophinopathies, suggesting that the absence of dystrophin might be related to increased central nervous system (CNS) excitability." (PMID 34640386, 2021). "Most extreme of all, it is possible, although highly unlikely in an individual with suspected dystrophinopathy, that an apparent duplication could be inserted elsewhere in the genome and hence not disrupt the DMD gene." (PMID 32424326, 2020). "Although we did not include patients with suspected dystrophinopathy in this study, we included DMD in the panel to detect DMD and BMD cases that may not have been suspected previously on the basis of clinical data." (PMID 32403337, 2020). "The NRSDS-BMD/DMD database could complement the TREAT-NMD database, especially for researchers who are interested in Chinese or Asian patients, as this is the largest hospital-based dystrophinopathy database not only in China but also in Asian countries." (PMID 33101180, 2020).